DYRK1A (dual specificity tyrosine phosphorylation regulated kinase 1A)
Diseases named in the same sentence as DYRK1A in open-access papers (continued):
Sharing a sentence is not in itself a finding about the gene and the disease.
tumor (continued). "Thus, the associations of the expression of TGF-β/SMAD signalling-related genes and the expression of DYRK1A with tumour metastasis were first investigated." (PMID 35655269, 2022). "We demonstrated that DYRK1A inactivation sensitized PC cells to X-rays, and targeted DYRK1A inhibitor Harmine strongly synergized with radiotherapy, leading to increased cell death and anti-tumor effect." (PMID 35053488, 2022). "In vivo, DYRK1A/B inhibition‐induced tumour stasis in a U87MG tumour xenograft model." (PMID 34708541, 2021). "For example, DYRK1A functions as a tumour suppressor in breast cancer and acute myeloid leukaemia." (PMID 33863878, 2021). "Inhibition of DYRK1A/B drives tumour cells out of quiescence (G0) and back into the cell cycle." (PMID 34708541, 2021). "Thus, our work adds DYRK1A to the small category of kinases that function as tumour suppressors, such as PKC and MKK438,39." (PMID 33863878, 2021). "However, a tumor suppressor role was also proposed on the basis of DYRK1A overexpression experiments in AML cells." (PMID 32751160, 2020). "A direct role for DYRK1A in tumor progression has been proposed in several studies." (PMID 32751160, 2020). "DYRK1A inhibitors have been comprehensively reviewed elsewhere, and so, we will only refer to the orally bioavailable archetypic DYRK1A inhibitors in tumor contexts." (PMID 32751160, 2020). "Thus, more research is clearly required to fully understand how DYRK1A contributes to tumor initiation or progression." (PMID 32751160, 2020). "In summary, the literature reflects a complex picture in which DYRK1A may fulfill opposite roles in different tumor contexts." (PMID 32751160, 2020). "Further, DYRK1A knock out conferred resistance to ionizing radiation in colony formation assays, suggesting that DYRK1A expression decreases cell survival efficiency in response to DNA damage and points to a tumor suppressive role for this kinase." (PMID 31024071, 2019). "How this mechanism relates to the effects of DYRK1A expression on radiosensitivity and the tumor suppressive signature revealed in the Kaplan-Meier analyses remain unclear." (PMID 31024071, 2019). "Inhibition of DYRK1A in vivo also resulted in a reduction in tumor growth." (PMID 27796319, 2016). "We observed a significant decrease in tumor load in mouse xenografts upon DYRK1A inhibition." (PMID 27796319, 2016). "Altogether, there is increasing evidence that inhibition of Dyrk1B, possibly in combination with Dyrk1A, might represent a promising, yet underexploited anti-tumor strategy." (PMID 24676346, 2014). "Our results clearly show DYRK1A acts as a potential tumor suppressor in AML." (PMID 24901999, 2014). "This strongly suggests that the DYRK1A has anti-tumor effects in adult." (PMID 24901999, 2014). "Our study provided functional evidences for DYRK1A as a potential tumor suppressor in AML." (PMID 24901999, 2014). "Interestingly, many of the anti-tumor mechanisms attributed to flavonoids such as fisetin, kaempferol, isorhamnetin, morin, myricetin, and quercetin closely overlap with the pathways regulated by DYRK1A." (PMID 40723805, 2025). "Notably, Dyrk1A is recognized as both tumor suppressor and oncogene." (PMID 37864462, 2024). "We suggest that the variation in DYRKs expression in normal vs. tumor samples and in different tumor stages as in case of DYRK1A might not be linked to mutations, instead it might be due to epigenetic alterations." (PMID 35454940, 2022). "Importantly, an inhibitor of DYRK1A/B AZ191 could inhibit tumor growth in mice for HCC cells with high level of TROAP." (PMID 33500384, 2021).
tumor (continued). "It was reported that DYRK1A could act as both an oncogene and a tumor suppressor." (PMID 34445786, 2021). "Similarly, lncRNA OIP5-AS1 can improve the radiosensitivity of tumor cells via inhibiting the expression of miR-369-3p, thus increasing the expression of dual-specificity tyrosine-(Y)-phosphorylation regulated kinase 1A (DYRK1A), the downstream gene of miR-369-3p." (PMID 32122355, 2020). "Therefore, as will become evident below, it remains unclear as to whether DYRK1A acts as a tumor suppressor or a tumor promoter or, more probably, as either, depending on the tumor context." (PMID 32751160, 2020). "Other protective genes, including DYRK1A, DICER1, MYOD1 and INTS6, also contribute to tumor suppression through diverse mechanisms." (PMID 40561176, 2025). "Notably, tumor cells isolated from the Bcl6 transgenic and the Myc/Bcl6 transgenic mice displayed reduced Dyrk1a mRNA expression levels, indicating that Dyrk1a may be negatively regulated either by Bcl6 or Myc in these models." (PMID 40148558, 2025). "The effects of DYRK1A gene silencing were even more pronounced in TNBC, showing a strong reduction in both tumor volume and tumor weight at experimental endpoint." (PMID 38839871, 2024). "In agreement with our flow cytometry findings, we found that DYRK1A inhibition leads to increase in expression of G1/S regulators (i.e. Cyclin D1, and CDK4) and a decrease in expression of CENP-A in tumor samples." (PMID 38839871, 2024). "Regarding the promoting effect of DYRK1A on cell invasion, the results showed that DYRK1A was coexpressed with TGF-β/SMAD and STAT3 signalling components in clinical tumour samples obtained from patients with HCC." (PMID 35655269, 2022). "This difference is reminiscent of the DYRK kinase family, in which DYRK1A usually acts as an oncogene, while DYRK1B and DYRK3 inhibit tumor progression." (PMID 35092699, 2022). "The expression of DYRK1A and DYRK3 expression correlated with immune-infiltrating cells in the tumor microenvironment and was upregulated in MSI subtypes, pointing to their potential role as biomarkers for immunotherapy." (PMID 35454940, 2022). "Herein, DYRK1A was found to be coexpressed with members of the TGF-β/SMAD and STAT3 signalling pathways in clinical tumour samples from patients with HCC." (PMID 35655269, 2022). "For instance, a study revealed that DYRK1A can modulate the expression of c-mesenchymal-epithelial transition receptor (c-MET) and drive tumour growth, and it was therefore considered a target for treating pancreatic ductal adenocarcinoma." (PMID 35655269, 2022). "Among these genes, only DYRK1A, VPS4B, PLAGL2, these three genes have been reported to act as tumor-promoter in HCC." (PMID 33596983, 2021). "On the other hand, DYRK1A inhibition promotes EGFR degradation in primary GBM cells, thus compromising their survival and producing a profound decrease in tumor burden." (PMID 31035417, 2019). "Notably, NSUN6 emerged as the most influential protective factor, followed by other tumor‐suppressive genes such as CPEB3, RCL1 and DYRK1A." (PMID 40561176, 2025). "Similarly, DYRK1A inhibition suppressed the EGFR/c-Met signaling in pancreatic cancer, resulting in a decreased tumor growth." (PMID 37900285, 2023). "DYRK1A was found to be coexpressed with several STAT3 target genes, including zinc finger E-box-binding homeobox 1, VEGFA and heat shock protein 90, in clinical tumour samples from patients with HCC." (PMID 35655269, 2022). "This indicates that among DYRKs members, only DYRK1A is overexpressed in later tumor stages of CRC patients and suggests that DYRK1A may play a role in the advanced stages of the disease." (PMID 35454940, 2022). "Furthermore, DYRK1A and TSC1 were coexpressed in clinical tumour samples from patients with HCC (Spearman correlation analysis; r = 0.61, p < 9.4e–39; Pearson correlation analysis, r = 0.62, p < 0.0001)." (PMID 35655269, 2022).
tumor (continued). "Finally, we demonstrate that blocking peptides competitively inhibit the effect of DYRK1A on NFATC1, clearly reducing NFATC1 protein and impairing tumor migration." (PMID 34309232, 2021). "DYRK1A is expressed in neuronal and non-neuronal tissues during development and adulthood and has been described to contribute to tumor development, both as an oncogene and as a tumor suppressor." (PMID 34983389, 2022). "However, whether DYRK1A is connected to alterations in these pathways during tumor initiation/progression has not yet been established." (PMID 32751160, 2020). "However, the role of DYRK1A as a negative or positive effector of tumor progression could be complex and tumor cell-dependent." (PMID 30979931, 2019). "Both DYRK1A and DYRK2 showed a significantly lower expression in READ tumor vs. normal tissues, whereas DYRK1B, DYRK3 and DYRK4 had no significant change in expression." (PMID 35454940, 2022). "In contrast, DYRK1B and DYRK4 tumor expression was not correlated to MYCN amplification status, and DYRK1A was actually lower in tumors with MYCN amplification." (PMID 29977157, 2018). "However, the unbiased analysis of differentially expressed genes in human tumour samples has revealed that the expression of DYRK1B, but not DYRK1A, is elevated in various types of solid tumours." (PMID 39397076, 2024).
neurodegenerative disease (37 papers, 2014 to 2026). A disorder of the central nervous system characterized by gradual and progressive loss of neural tissue and neurologic function. "DYRK1A is also associated with neuroinflammation which is implicated in neuronal damage and the onset of neurodegenerative diseases." (PMID 34828439, 2021). "Septin 4 (SEPT4), a GTPase previously found in neurofibrillary tangles of AD and in LB was also found to be a substrate of DYRK1A in neocortical neurons, expanding the mechanisms by which DYRK1A is implicated in neurodegenerative diseases." (PMID 34828439, 2021). "DYRK1A controls dendritic development and spine formation and its deregulation has been implicated in neurodevelopmental and degenerative diseases." (PMID 32032735, 2020). "DYRK1A dysregulation is implicated in neurodegenerative diseases, notably Down syndrome and AD." (PMID 41009744, 2025). "Additionally, DYRK1A is associated with neurodegenerative diseases." (PMID 37274198, 2023). "DYRK1A, for dual specificity tyrosine-phosphorylation-regulated kinase 1A, is a serine/threonine kinase that, when overexpressed in brain, contributes to the neurodegeneration, neuronal death, and loss of function observed in multiple neurodegenerative diseases." (PMID 30172984, 2018). "Our research highlights the critical role of selective DYRK1A inhibitors in treating neurodegenerative diseases and presents a promising starting point for the development of targeted therapies." (PMID 39494990, 2024). "Collectively, these data suggest that DYRK1A is a potentially viable target for the treatment of neurodegenerative diseases involving a neuroinflammatory component, such as in PD." (PMID 36986543, 2023). "Although the tau kinases DYRK1A and GSK3α/β play key roles in the effects of LPS in the CNS and neurodegenerative diseases such as AD, few studies have investigated the effects of calcium channel blockers on tau kinase activity in vivo." (PMID 37435081, 2023). "Dual-specific tyrosine phosphorylation regulated kinase 1 (DYRK1A) has been regarded as a potential therapeutic target of neurodegenerative diseases, and considerable progress has been made in the discovery of DYRK1A inhibitors." (PMID 35335117, 2022). "Due to its involvement in a multitude of neural development and neuronal signaling pathways, DYRK1A activity has received increased interest as a key contributing factor to neurodevelopmental and neurodegenerative diseases." (PMID 36012629, 2022). "Recently, it has been demonstrated that increased DYRK1A levels were present in the brains of patients not only with AD but as well as other neurodegenerative diseases such as PD, HD and FTD syndromes." (PMID 36012629, 2022). "At present, a diversity of DYRK1A inhibitors were identified as potential therapies for neurodegenerative diseases including natural product harmine and synthetic compounds, benzothiazoles, azaindoles, pyrazolo, pyridine, pyrimidine, and quinazolines." (PMID 35335117, 2022). "While DYRK1A has been proven to be an essential regulator in normal brain development and neurodegenerative diseases, the gaps still exist in our knowledge regarding its functional activities in tumourigenesis." (PMID 33860868, 2021). "More recently, the knowledge that Alzheimer-associated proteins Tau and APP (discussed earlier) are DYRK1A substrates has attracted the study of DYRK1A inhibitors in neurodegenerative disease in general." (PMID 34335466, 2021). "This off-target effect might induce unwanted outcomes, highlighting the importance of developing specific inhibitors for DYRK1A-related neurodegenerative diseases (NGDs)." (PMID 39494990, 2024). "A recent study suggests that elevated plasma levels of DYRK1A might help prevent neurodegenerative diseases, highlighting the potential value of this target in detecting, monitoring, and managing neurodegenerative disorders." (PMID 38212778, 2024). "Inhibiting DYRK1A may have therapeutic potential in neurodegenerative disease models." (PMID 41009744, 2025).
neurodegenerative disease (continued). "Dual-specificity tyrosine phosphorylation-regulated kinase 1A (DYRK1A) is a protein kinase with diverse functions in neuronal development and adult brain physiology, and its enhanced levels are associated with the pathology of neurodegenerative diseases like AD." (PMID 36918783, 2023). "We seek to develop a potent and selective negative allosteric modulator of “Dual-specificity tyrosine-(Y)-phosphorylation Regulated Kinase-1A” (DYRK1A) to treat neuroinflammatory and neurodegenerative diseases such as Parkinson’s disease (PD)." (PMID 36986543, 2023).
neurological diseases (13 papers, 2016 to 2026). "The gain or loss of function of Dyrk1A due to abnormal truncation can affect neuronal development or neurodegeneration in neurological disorders." (PMID 37864462, 2024). "DYRK1A distributes in different types of neuronal cells in the human brain and has been found to be associated with neurological diseases, such as Down syndrome (DS), autism, and neurodegenerative diseases." (PMID 36830653, 2023). "Among the dual-specificity tyrosine (Y)-phosphorylation-regulated kinase (DYRK) family, DYRK1A has been given considerable attention concerning neurological diseases." (PMID 41009744, 2025). "These evidences suggest that the transcriptional activation domain is a potential therapeutic target for DYRK1A-related neurological diseases apart from its kinase domain." (PMID 36830653, 2023). "Our finding provides novel understanding on the function of DYRK1A and suggests that the transcriptional activation domain is a potential target for the therapy of DYRK1A-related neurological diseases." (PMID 36830653, 2023). "Given the involvement of Dyrk1A in severe and common neurological diseases, a number of efforts have been put into developing competitive small chemical inhibitors against Dyrk kinase activity, and several of such inhibitor compounds are currently available." (PMID 34090874, 2021). "Thus, manipulating DYRK1A activity in the brain has emerged as a potential therapeutic target for neurological disorders." (PMID 41676546, 2026). "We next compared our genes to gene sets of ASD or other neurological disorders and found that CHD8, DYRK1A, GRIN2B, MBD5 and SCN2A overlapped with the ASD gene sets (FDR ≤ 0.1) reported in previous large-scale ASD studies." (PMID 32193494, 2020).
neurodevelopmental disorder (12 papers, 2016 to 2025). A behavioral and cognitive disorder with onset during the developmental period that involves impaired or aberrant development of intellectual, motor, or social functions. "DYRK1A syndrome is a well-established neurodevelopmental disorder caused by heterozygous variants in the DYRK1A gene leading to haploinsufficiency." (PMID 40405340, 2025). "Executive functioning, higher order cognitive processes that strongly impact behavioral functioning, has been shown to be an area of challenge among neurogenetic and neurodevelopmental disorders that are associated with DYRK1A." (PMID 39840013, 2024). "By characterizing DYRK1A’s interactome in human neural stem cells, its effects on gene expression, and its functional impact on proliferation, we reveal critical insights into its role in brain development and the molecular basis of associated neurodevelopmental disorder." (PMID 40182141, 2025). "The findings shed light on how DYRK1A interacts with proteins or regulates the expression of genes known to be involved in neurodevelopmental disorders (NDDs)." (PMID 40182141, 2025). "The phenotypic follow-up of cases of neurodevelopmental disorders has allowed to explore specific clinical phenotypes in a genotype-first manner, such as in the case of genes such as DYRK1A and activity-dependent neuroprotective protein (ADNP)." (PMID 35740400, 2022). "Key calcium signaling effectors like DYRK1A are deregulated both in neurodevelopmental disorders and cortices of sporadic AD patients." (PMID 36102617, 2022). "These two neurodevelopmental disorders share common features resulting from the alteration of DYRK1A-controlled mechanisms such as neuronal proliferation and differentiation." (PMID 27375444, 2016).